KIF9 (kinesin family member 9)
Description:
Essential for normal male fertility and for progressive motility of spermatozoa.
Synonyms: MGC104186
Tractability: Small molecule: a structure with a bound ligand is known. PROTAC: ubiquitination databases record sites on it.
Target class: Other cytosolic protein
Gene: Protein-coding gene on chromosome 3 (47,227,998 to 47,283,451, reverse strand). Ensembl gene ENSG00000088727.
Subcellular location: Cytoplasm, cytoskeleton; Cell projection, cilium, flagellum; Cytoplasm, cytoskeleton, flagellum axoneme
Subcellular location (Human Protein Atlas): Cytosol; Primary cilium; Primary cilium tip; Mid piece
Pathways (Reactome):
Hemostasis: Kinesins
Vesicle-mediated transport: COPI-dependent Golgi-to-ER retrograde traffic
Gene Ontology:
Molecular function: identical protein binding; protein binding; ATP binding; microtubule binding; microtubule motor activity
Biological process: extracellular matrix disassembly; organelle disassembly; regulation of podosome assembly; regulation of flagellated sperm motility; microtubule-based movement
Cellular component: microtubule; podosome; vesicle; kinesin complex; sperm flagellum; axonemal microtubule; cytoskeleton; motile cilium; plasma membrane bounded cell projection
Genetic constraint (gnomAD): Loss-of-function variants: 60 observed, 85.2 expected, observed/expected ratio (o/e) 0.7, 90% interval 0.57 to 0.87. The upper end of that interval is the gene's LOEUF score, 0.87, which puts it in group 3 of 6, group 1 being the genes least tolerant of losing a copy. Missense variants: 854 observed, 989.87 expected, observed/expected ratio (o/e) 0.86, 90% interval 0.81 to 0.91. Synonymous variants: 331 observed, 371.07 expected, observed/expected ratio (o/e) 0.89, 90% interval 0.81 to 0.98.
Homologues: Orthologues: chimpanzee KIF9 (99% identical), dog KIF9 (92% identical), pig KIF9 (92% identical), rat Kif9 (89% identical), mouse Kif9 (89% identical), macaque KIF9 (89% identical), guinea pig KIF9 (88% identical), tropical clawed frog kif9 (61% identical). Paralogues in human: KIF6 (30% identical), KIF15 (26% identical), KIF16B (23% identical), KIF1B (22% identical), KIF1A (22% identical), CENPE (22% identical), KIF13A (21% identical), KIF21B (21% identical), KIF13B (21% identical), KIF27 (21% identical), KIF21A (21% identical), KIF7 (21% identical), and 29 more.
Diseases named in the same sentence as KIF9 in open-access papers:
KIF9 is named in the same sentence as 23 diseases in open-access papers, as found by Europe PMC text mining. Sharing a sentence is not in itself a finding about the gene and the disease. The quoted sentences say what the papers report.
asthenospermia (2 papers, 2020 to 2022). "Because Kif9 is conserved in humans, revealing how KIF9 regulates flagellar motility may lead to better treatment for individuals with asthenozoospermia." (PMID 32072696, 2020).
Hydrocephalus (2 papers, 2020 to 2025). Hydrocephalus is an active distension of the ventricular system of the brain resulting from inadequate passage of CSF from its point of production within the cerebral ventricles to its point of absorption into the systemic circulation. "The milder phenotype of Kif9 mutant mice compared to Hydin KO mice, such as subfertility, no abnormalities in axonemal ultrastructures, or no overt hydrocephalus, may be due to the compensation by KIF6." (PMID 32072696, 2020).
infertile (2 papers, 2022). "Notably, in vitro fertilization (IVF) was able to successfully overcome the infertility issues facing these two KIF9-deficient patients." (PMID 36686457, 2022). "Detailed description of the biallelic variants in KIF9 identified in two infertile men with AZS." (PMID 36686457, 2022). "Both of these men exhibited typical AZS and suffered from infertility together with the complete absence of KIF9 expression." (PMID 36686457, 2022).
male infertility (2 papers, 2022 to 2025). The inability of the male to effect fertilization of an ovum after a specified period of unprotected intercourse. "This study is the first report demonstrating a link between KIF9 variants and the incidence of male infertility among humans, thus expanding the known catalog of AZS-related genes." (PMID 36686457, 2022). "Deletion of murine Kif9 impairs flagellar motility of sperm, resulting in male infertility." (PMID 36686457, 2022).
astrocytoma (1 paper, 2019). "Additionally, we observed that the mRNA levels of KIF4A, KIF9, KIF18A, and KIF23 were elevated in LGG patients with a higher histological grade and astrocytoma histologic type than in those with a lower histological grade and histologic type, including oligoastrocytoma and oligodendroglioma." (PMID 30872592, 2019).
breast carcinoma (1 paper, 2021). "It has been mentioned that KIF9 may be related to the occurrence of breast cancer." (PMID 34346563, 2021).
Cognitive impairment (1 paper, 2025). Abnormal cognition is characterized by deficits in thinking, reasoning, or remembering. "Importantly, genetic upregulation of KIF9 via adeno‐associated virus (AAV) diminished Aβ deposition and alleviated cognitive impairments in AD model mice by enhancing macroautophagy function." (PMID 39829171, 2025). "Genetic upregulation of KIF9 enhances macroautophagy by promoting KLC1‐mediated anterograde transport of lysosomes, which effectively reduces Aβ deposition and alleviates cognitive impairments in AD." (PMID 39829171, 2025).
colorectal cancer (1 paper, 2022). A primary or metastatic malignant neoplasm that affects the colon or rectum. "We also performed the same analysis of renal and colorectal cancer patients with low or high mRNA expression of the Kif9 gene." (PMID 35122963, 2022).
Crohn disease (1 paper, 2023). A gastrointestinal disorder characterized by chronic inflammation involving all layers of the intestinal wall, noncaseating granulomas affecting the intestinal wall and regional lymph nodes, and transmural fibrosis. "Interestingly, two of these SNPs, rs3772479 and rs2270569, are located in the FHIT and KIF9 genes, respectively, which have been reported to play an important role in inflammatory bowel disease (IBD) (Crohn’s disease being a type of IBD)." (PMID 37337586, 2023).
Senile plaques (1 paper, 2025). Senile plaques are extracellular deposits of amyloid in the gray matter of the brain. "Notably, KIF9 overexpression through AAVKIF9 significantly reduced the number of senile plaques in AD model mice." (PMID 39829171, 2025).
cancer (4 papers, 2017 to 2022). A tumor composed of atypical neoplastic, often pleomorphic cells that invade other tissues. "In this study, high KIF9 expression was associated with cancer progression and showed significantly poor survival, especially in GBM patients." (PMID 30872592, 2019). "The analysis of the TCGA database revealed that the expression profile of KIF13A and KIF9 is altered in several cancer types." (PMID 35122963, 2022). "We next investigated if the expression level of KIF3A, KIF13A, and KIF9 correlates with cancer progression." (PMID 35122963, 2022). "Thus, KIF9 may have an anti-tumorigenic potential for these two cancer types." (PMID 35122963, 2022). "However, no study on the relationship between KIF9 and cancer has been reported to date." (PMID 30872592, 2019).
tumor (2 papers, 2016 to 2021). "The MDR included the CCDC12, NBEAL2, SETD2, KIF9 and KLHL18 genes, of which SETD2 was the most significantly underexpressed in tumour cells." (PMID 27282254, 2016).
KIF9 also shares sentences with these, for which no sentence is quoted: glioma (2 papers); Alzheimer disease (1); Anxiety (1); bladder tumors (1); congenital hydrocephalus (1); glioblastoma (1); inflammatory bowel disease (1); oligoastrocytoma (1); oligodendroglioma (1); prostate carcinoma (1); thyroid cancer (1).